RAB1A (RAB1A, member RAS oncogene family)
Diseases named in the same sentence as RAB1A in open-access papers (continued):
Sharing a sentence is not in itself a finding about the gene and the disease.
cancer (continued). "In contrast, compare the early and advanced gastrointestinal relevant cancer, Rab1A expression was not statistically different." (PMID 31527621, 2019). "Clathrin, caveolin, Rabs (Rab4, Rab5A, Rab1A, Rab2A) as well as their effectors (Rab25, Vav1, Rab coupling protein,cdc42, VSP39), can contribute to the processes of cancer cell survival and metastasis, and cancer stem cell emergence." (PMID 29409507, 2018). "Conversely, RAB1A knockdown selectively attenuates oncogenic growth and invasion of cancer cells with high RAB1A expression, while not significantly affecting those tumors with low RAB1A expression." (PMID 26590354, 2015). "However, the precise molecular mechanisms of Rab1A in the regulation of radioresistance and cancer metastases in NPC have not yet been unravelled." (PMID 33068388, 2020).
infection (10 papers, 2015 to 2023). The state of being infected such as from the introduction of a foreign agent such as serum, vaccine, antigenic substance or organism. "To assess the effect of the Rab family on RSV replication, we depleted Rab1a, Rab2a, Rab4a, Rab5a, Rab6a, Rab7a, Rab8a, Rab9a, and Rab11a by treating A549 cells with specific siRNAs (or control siRNA) for 24 h, followed by infection with purified RSV A2 and incubation for another 36 h." (PMID 33504607, 2021). "Importantly, the data suggests that ubiquitin, annexin A1, annexin A2, MavP are putative novel interaction partners and that Rab1A, Rab1B, Rab6, and Rab10 are the predominant Rab GTPases targeted by SidM during infection." (PMID 26755725, 2016). "Rab1 is upregulated in the kidney of red drum in response to intracellular bacteria Edwardsiella tarda during 4- to 24-h time periods of infection, and Rab-1A, Rab-6A, and Rab-10 proteins have been upregulated persistently in the liver of gilthead sea bream profile after confinement exposures." (PMID 25563603, 2015). "For example, Rab1A is critical for infection by the pathogen Legionella pneumophila." (PMID 26308575, 2015). "Our results revealed that the dominant-negative Rab1A abolished the maturation of EBV glycoprotein gp350/220 and reduced mature virion release and the infection of Raji cells." (PMID 36602343, 2023). "After infection, we compared the number of G-elements between cells expressing either GFP or wild-type Rab1a (Rab1aWT) as controls, and the respective DN mutant (Arf1DN or Rab1aDN) cells." (PMID 34013963, 2021). "Hence, we analyzed the infection-related localization of both, RAB1A and RAB1B, and detected a partial and a strong colocalization of RAB1A and RAB1B, respectively, with SIF." (PMID 32658937, 2020). "While we were able to identify protein spots for each complex, Rab1a-Dynll1, Snx2-Dynll1, and Canx-Dynll1 were not measurably altered by infection." (PMID 32041786, 2020).
Neurological Disorder (2 papers, 2009 to 2023). "In light of the results presented here, we propose that it is the function of Rab1A in autophagy that is important for its role in neurological disorders." (PMID 36781179, 2023).
kidney diseases (1 paper, 2023). "It is good to keep in mind that the uEV reference mRNA candidates could be contributing to biological processes associated with kidney diseases e.g., RAB1A contributes to autophagy." (PMID 37510317, 2023).
respiratory disease (1 paper, 2010). "On the other hand, as for other nearby potential genes in the region where CEP68 is located, the RAB1A gene, despite the lack of reports showing direct relations with aspirin and/or respiratory disease, was also found to be associated with AIA by composing a strong LD with CEP68 (P<0.01)." (PMID 21072201, 2010).
RAB1A also shares sentences with these, for which no sentence is quoted: adenocarcinoma (2 papers); cervical cancer (2); colorectal (2); COVID-19 (2); adenoma (1); adenosquamous carcinoma (1); amyotrophic lateral sclerosis (1); bile duct cancer (1); bladder tumor (1); cholangiocarcinoma (1); diabetes (1); esophageal carcinoma (1); gastrointestinal tumor (1); heart failure (1); hepatitis B virus infection (1); hydronephrosis (1); Insulin resistance (1); Intellectual disability (1); intellectual impairment (1); large cell lung cancer (1); learning disabilities (1); oral cancers (1); pan (1); pancreatic adenocarcinoma (1); pancreatic ductal adenocarcinoma (1); prostate (1); prostate tumors (1); rectum adenocarcinoma (1); squamous cell carcinoma (1); stomach adenocarcinoma (1).
A further 3 diseases each share a sentence with RAB1A in 1 paper.